DSG1 (desmoglein 1)
Diseases named in the same sentence as DSG1 in open-access papers (continued):
Sharing a sentence is not in itself a finding about the gene and the disease.
keratoconus (1 paper, 2023). A degenerative, structural disorder of the eye, characterized by a cone-shaped protrusion of the cornea. "For instance, several cadherin-family proteins, such as cadherin 11 and desmoglein 1, are known biomarkers for keratoconus, and N-cadherin is critical for corneal epithelial cell maturation." (PMID 37561511, 2023).
osteosarcoma (1 paper, 2020). A usually aggressive malignant bone-forming mesenchymal neoplasm, predominantly affecting adolescents and young adults. "Protein OS-9 involved in the ubiquitination of misfolded proteins was identified for the first time in a human osteosarcoma cell line, while desmoglein-1 was reported to interact with the testis-specific isoform of Na/K ATPase in the plasma membrane of bovine sperm during capacitation." (PMID 32942548, 2020).
plantar wart (1 paper, 2017). A wart in the plantar surface of the foot. "For example, two genes involved in innate immunity of skin, LCE3E and DSG1, were significantly associated with plantar warts and yeast infections, respectively." (PMID 28928442, 2017).
skin fragility (1 paper, 2021). "KRT5 mutation altered the expression of DSG1, suggesting the regulatory role of this protein, thereby establishing that K5 contributes to the etiology of skin fragility directly or indirectly via DSG1." (PMID 34912369, 2021).
squamous intraepithelial lesions (1 paper, 2012). "In cervix, a tissue type that resembles the anal mucosa, DSG1 protein expression has been shown to be reduced during progression of squamous intraepithelial lesions (SILs)." (PMID 22333708, 2012).
visceral leishmaniasis (1 paper, 2020). A severe form of leishmaniasis characterized by irregular bouts of fever, substantial weight loss, swelling of the spleen and liver, and anemia (which may be serious). "Further, it has been demonstrated that anti-Dsg1 and -Dsg3 antibodies were more prevalent in subjects with visceral leishmaniasis." (PMID 33108348, 2020).
cancer (20 papers, 1990 to 2023). A tumor composed of atypical neoplastic, often pleomorphic cells that invade other tissues. "For example, membrane negativity for DSG1 and cytoplasmic negativity for DSG1 are favourable markers for 5-year cancer-specific survival in SCCs of the anal region." (PMID 32850288, 2020). "It was found that the expression of Dsg1 in cancer cell lines decreased or even disappeared compared to that in normal control cells." (PMID 32546690, 2020). "A reciprocal relationship between Dsg1 and neddylated EGFR was observed in a 3D carcinoma model, raising the possibility that loss of desmosomes during cancer progression unscaffolds membrane-associated CSN complexes, resulting in hyper-neddylated EGFR." (PMID 28891468, 2017). "A reciprocal relationship between loss of Dsg1 and neddylated EGFR was observed in a carcinoma model, consistent with a role in sustaining EGFR activity during tumor progression." (PMID 28891468, 2017). "Our finding that the effect of membranous DSG1 staining on CSS varies with E-cadherin levels in the tumours is difficult to explain from the limited knowledge on the role of desmosomes in cancers." (PMID 22333708, 2012). "Moreover, DSG1, C6orf15, SOST, SPRR2A, SERPINB7, MYBPH, and KRT1 were considerably expressed in the high-risk group, indicating their potential roles as cancer-promoting genes in the development of BLCA." (PMID 37664033, 2023). "In addition, while the majority of studies on DSG1 have focused on epithelial cells, we validated the expression and function of DSG1 in CML cells, suggesting that DSG1 may have broader relevance in this signaling pathway in other cell types and cancers." (PMID 35241148, 2022). "DSG1 and DSG3 are components of intercellular desmosome junctions, which mediate cell‐cell adhesion and correlate with EMT in cancer progression." (PMID 38090381, 2023). "Among these genes, DSG1 and DSG3 are components of intercellular desmosome junctions, which mediate cell‐cell adhesion and correlate with EMT in cancer." (PMID 38090381, 2023). "DSG1, a member of the desmoglein protein subfamily, plays a crucial role in cell adhesion, whose dysfunction promotes the process of epithelial-mesenchymal transition (EMT) and thus the invasion and metastasis of cancer cells." (PMID 32149116, 2020). "However, the level of Dsg1, and to a lesser extent Dp, is reduced in the SCC9 and 1483 cancer 3D rafts when compared to control, primary NHEK 3D rafts." (PMID 28891468, 2017). "Univariate analyses identified, among others, negative membranous DSG1 staining (P=0.009), negative cytoplasmic DSC1 staining (P=0.012) and negative DSG1 (membranous)+negative DSC1 (cytoplasmic) staining (P=0.004) to be associated with improved cancer-specific survival (CSS)." (PMID 22333708, 2012).
tumor (19 papers, 1997 to 2024). "Lower levels of DSG1, DSG3, and desmosome expression cause the loosening of desmosome adhesion, and cells subsequently leave the primary tumour, leading to tumour invasion and metastasis." (PMID 36291586, 2022). "Klk7 has been implicated in the cleavage of corneodesmosomal proteins, such as Cdsn and Dsc1, during terminal differentiation of the epidermis, and of Dsg1 in tumor cells." (PMID 32457102, 2020). "An earlier study showed that there is a correlation between the lower expression of DSG1 (human protein) and tumour invasion, lymph node metastasis, and lymphatic invasion, and DSG1 may be a significant factor in the prognosis of ESCC." (PMID 36291586, 2022). "In the interfollicular epidermis, DSG1 and DSG2 are normally expressed at very low level and restricted to the proliferative basal cell layer, leading to tumour cells with high DSG1 or DSG2 expression that often exhibit high malignancy, which is identified by all previous research." (PMID 32850288, 2020). "Thus inhibition of HGF can exert anti-tumor effect with maintaining cell-to-cell junctions via stabilizing desmosomes by DSG1 overexpression." (PMID 32564264, 2020). "Desmoglein-1 and keratin type I cytoskeletal 9 were down-regulated in tumor." (PMID 32564264, 2020). "In addition, medium expression of DSG1 was observed in normal tissues, while low expression of DSG1 was observed in tumor tissues." (PMID 32546690, 2020). "Serum anti-skin antibodies were significantly higher in the patients than in the controls (p = 0.008, p < 0.001, p < 0.001, p < 0.001 and p < 0.001 for desmoglein 1 (DSG1) desmoglein 3 (DSG3), bullous pemphigoid 180 (BP180), BP230 and type VII collagen (COL7), respectively)." (PMID 27669234, 2016). "For DSG1 membrane staining, 31% of the tumours were scored positive." (PMID 22333708, 2012). "All anti-skin antibodies were significantly higher in the EB patients than in the controls (p = 0.008, p < 0.001, p < 0.001, p < 0.001 and p < 0.001 for desmoglein 1 (DSG1), desmoglein 3 (DSG3), bullous pemphigoid 180 (BP180), BP230 and type VII collagen (COL7), respectively)." (PMID 27669234, 2016). "The upregulation of DSG1 and/or DSG2 is related to enhanced tumour progression and/or shorter patient survival." (PMID 32850288, 2020). "We observed that the expression of DSG1 and DSG2 in EHCC tumour tissues presented a significant downregulation compared to the nontumour tissues." (PMID 32850288, 2020). "The expression of the DSG1 and DSG2 proteins was significantly lower in EHCC tumour tissues than in normal biliary tract tissues, biliary tract adenoma, and peritumoral tissues (P < 0.05)." (PMID 32850288, 2020). "We first found DSG1 down-regulated in LHSCC with LC/MS, albeit rather isoform switch among desmogleins seems to be determining in tumor invasivity." (PMID 32564264, 2020). "Although the expression of DSG1 and DSG2 has been proven to be involved in the progression and prognosis of certain types of tumours, the expression and significance of DSG1 and DSG2 in EHCC have not been previously reported." (PMID 32850288, 2020). "The protein expression of DSG1 and DSG2 was measured by EnVision immunohistochemistry in 15 normal biliary tract tissues, 10 biliary tract adenoma tissues, 30 peritumoral tissues, and 100 EHCC tumour tissues." (PMID 32850288, 2020). "Furthermore, other members of the desmosomal cadherin family were expressed at low level in a small number of TCGA tumors, and DSG1, DSC2 and DSC3 were all significantly enriched in the DSG2-high tumor subset." (PMID 27340778, 2016). "In the desmosome, they bind to DSG1 and DSC1 and may thereby act as tumour suppressors by stabilising intercellular adhesion." (PMID 22333708, 2012). "The overall P-value is 0.020, meaning that the finding of better survival in patients with tumours negative for DSG1 membrane staining is still valid when we adjust for E-cadherin expression." (PMID 22333708, 2012).
tumor (continued). "When DSG1 (membrane) and DSC1 (cytoplasmic) were categorised as one variable, the outcome for the patients with tumours staining positive for both DSG1 membranous and DSC1 cytoplasmic protein was significantly worse than for the patients with no staining for DSG1 and DSC1." (PMID 22333708, 2012). "Thus, both DSG1 and DSG2 may inhibit tumour progression in EHCC, and function as prognostic biomarkers." (PMID 32850288, 2020). "Furthermore, KLK7 may stimulate tumor cell invasion and metastasis through cleaving extracellular matrix (ECM) proteins and several adhesion molecules, such as desmoglein-1 and desmocollin-1." (PMID 33087135, 2020). "The upregulation of Dsg1 and 2 upon Dsg3 loss may compensate for deficiency in some Dsg3 functions and could explain the lack of phenotypes in the UVB-induced tumor model." (PMID 23185521, 2012). "In addition, negative expression of DSG1 and DSG2 was closely associated with several clinicopathological characteristics of EHCC, which could present aggressiveness and determine the malignant degree of the tumour." (PMID 32850288, 2020).
infection (8 papers, 2015 to 2024). The state of being infected such as from the introduction of a foreign agent such as serum, vaccine, antigenic substance or organism. "This decreased DSG1 expression was associated with increased permeability of the genital tissues and enhanced susceptibility to intravaginal infection with herpes simplex virus–2 and HIV." (PMID 35533147, 2022). "ETA and ETB exfoliative toxins hydrolyze desmoglein 1, a cadherin responsible for the integrity of the adhesive structures, resulting in skin exfoliation, and lead to the destruction of the epidermal barrier facilitating the efficient progression of infection." (PMID 32448145, 2020). "The frequency of expression of CAPN14 and DSG1 was similar between the negative pre-infection and the negative control group." (PMID 36482106, 2022).
inflammation (2 papers, 2015 to 2022). Aberrant reaction of the microcirculation characterized by movement of fluid and leukocytes from the blood into extravascular tissues. "Furthermore, the loss of DSG1 expression might potentiate allergic inflammation through induction of proinflammatory mediators." (PMID 26073755, 2015).
genodermatosis (1 paper, 2015). "We studied a new case of SAM syndrome known to have no mutations in DSG1 to detail the clinical, histopathologic, immunofluorescent, and ultrastructural phenotype and to identify the underlying molecular mechanisms in this rare genodermatosis." (PMID 26073755, 2015).
infectious disease (1 paper, 2019). A disorder directly resulting from the presence and activity of a microbial, viral, or parasitic agent in humans. "DSG1 is directly linked with the cleavage of apoptotic proteins and via ROCK1 with MAPK signaling and infectious diseases (WDR1)." (PMID 31138830, 2019).
DSG1 also shares sentences with these, for which no sentence is quoted: ichthyosis vulgaris (3 papers); Netherton syndrome (3); colorectal cancer (2); erythroderma (2); IgA pemphigus (2); lichen planus (2); metastatic melanoma (2); paraneoplastic pemphigus (2); systemic lupus erythematosus (2); thrombotic thrombocytopenic purpura (2); adenocarcinoma (1); allergic rhinitis (1); amyloidosis (1); aortic valve disease (1); atherosclerosis (1); celiac disease (1); cervical tumours (1); connective tissue diseases (1); coronary heart disease (1); cutaneous melanoma (1); cutaneous T-cell lymphoma (1); Deep Venous Thrombosis (1); eczema (1); Fibroadenoma (1); glioblastoma (1); heart failure (1); hypotrichosis (1); interstitial lung disease (1); invasive breast carcinoma (1); IPEX syndrome (1).
A further 23 diseases each share a sentence with DSG1 in 1 paper.